LEP (leptin)
Diseases named in the same sentence as LEP in open-access papers (continued):
Sharing a sentence is not in itself a finding about the gene and the disease.
Insulin resistance (continued). "Several studies have shown that leptin levels are positively correlated with BMI, waist circumference, hip circumference, and insulin resistance parameters." (PMID 36499312, 2022). "The inflammatory cytokines produced by M1 macrophages neutralize the insulin-sensitizing actions of the hormones adiponectin and leptin, which eventually lead to insulin resistance." (PMID 36466412, 2022). "Leptin can antagonize insulin and produce insulin resistance, while adiponectin can improve insulin sensitivity by increasing fatty acid oxidation and glucose uptake in skeletal muscle cells." (PMID 35056765, 2022). "One study on 582 Irish women and their children reported higher concentrations of C-peptide and Leptin in the UC blood of the female infants and lower insulin resistance in their mothers." (PMID 36224521, 2022). "Leptin and insulin resistance has been traced back to an intracellular signaling pathway in which leptin is responsible for activation." (PMID 35328862, 2022). "It is well known that leptin and insulin resistance are important contributors to hyperphagia, thermogenesis dysfunction and inflammation." (PMID 36188456, 2022). "PEA, a non-canonic endocannabinoid, is recognized as an insulin sensitizer and AMPK activator, able to improve hepatic lipid and glucose homeostasis, steatosis, insulin resistance and serum leptin/adiponectin ratio." (PMID 35214069, 2022). "In type 2 diabetes, insulin resistance was found to correlate with leptin levels; it is possible that the hyperleptinemia found in these subjects reflects leptin resistance." (PMID 36289903, 2022). "Taurine is a type of abundant amino acid that existed in all mammalian tissues, which can improve the disorders of glucose metabolism and lipid metabolism by decreasing serum leptin levels and insulin resistance." (PMID 36120310, 2022). "We identified endocrine mechanisms, including those related to leptin and insulin resistance, as potential drivers of aetiological relationships of both generalised and central obesity with female reproductive health." (PMID 35104295, 2022). "It is notable that, with overfeeding, a situation of hyperleptinaemia quickly develops, accompanied by leptin, ghrelin, and insulin resistance and also by the blocking of the intracerebral effects." (PMID 36294794, 2022). "They include hemodynamic alterations, oxidative stress, renal injury, hyperinsulinemia, and insulin resistance, sleep apnea syndrome and the leptin-melanocortin pathway." (PMID 36293177, 2022). "We identified two clusters of individuals differentiated by abnormalities in insulin resistance, leptin levels, and hippocampal connectivity, with one of the clusters showing greater deviance." (PMID 35492025, 2022). "In this study we found significant reductions in the exercise group compared with usual care in pro-inflammatory biomarkers including TNF-α, IL-6, IL-8, hs-CRP or leptin, and those related to insulin resistance." (PMID 35795051, 2022). "The relationship between leptin and insulin resistance among middle-aged and elderly populations in Asia is seldom reported." (PMID 36143007, 2022). "Intrauterine exposure to hyperglycemia leads to the development of both leptin and insulin resistance in the placenta, and these alterations are related to maternal glycemic levels." (PMID 35706903, 2022). "Mice had elevated levels of plasma leptin and insulin and increased Homeostatic Model Assessment for Insulin Resistance (HOMA-IR) indicators of insulin resistance." (PMID 35910891, 2022). "GlycA is shown to be positively correlated with insulin resistance, BMI, markers of metabolic syndrome, and the ratio of leptin to adiponectin." (PMID 36501195, 2022). "Leptin has shown positive correlations with high C-reactive protein levels, as well as with insulin resistance, which have been shown to be related to CKD." (PMID 35619087, 2022).
Insulin resistance (continued). "We also studied the leptin–adiponectin ratio, as it is thought to be a better determinant of insulin resistance and metabolic alterations than leptin or adiponectin levels alone." (PMID 35629157, 2022). "MO mothers showed higher body weight, triglycerides and leptin serum concentrations, insulin resistance (IR), decreased small and increased large adipocytes, liver fat accumulation, and hepatic upregulation of genes related to IR and inflammatory processes." (PMID 36290594, 2022). "Visceral fat has a detrimental impact on insulin sensitivity as adipose tissue is linked with unfavourable secretion of hormones and pro-inflammatory chemicals, glycerol, leptin, cytokines, and lower secretion of adiponectin exacerbating insulin resistance." (PMID 36297122, 2022). "In conclusion, serum leptin levels showed a positive relationship with insulin resistance in middle-aged and elderly people in Taiwan." (PMID 36143007, 2022). "Leptin has a role in signaling full energy stores and decreasing appetite, and leptin concentration correlates positively, similar to resistin levels, with insulin resistance and body adiposity." (PMID 35509177, 2022). "Biomarkers such as homeostasis model of assessment for insulin resistance index (HOMA-IR), leptin, and leptin/adiponectin have been associated with components of MS and have been associated with a greater risk of MS among ALL children." (PMID 35386254, 2022). "In cachexia, the appetite regulation by leptin is impaired, and its role in insulin resistance can be important in worsening catabolic status of skeletal muscle." (PMID 36158184, 2022). "High serum insulin and leptin levels are early indicators of insulin resistance and impairments in glucose metabolism/prediabetes." (PMID 35807769, 2022). "The BSME-treated, maturing, adipocyte-secreted proteins were detected with a decreased protein level of leptin, TNF-α, IL-6 and STAT-6, which are associated with insulin resistance and macrophage recruitment." (PMID 35209178, 2022). "Central leptin infusion improves hepatic insulin resistance and markedly inhibits glucose production." (PMID 35742928, 2022). "We identified two clusters of increasing metabolic deviance primarily differentiated by the plasma levels of leptin and the degree of insulin resistance, as inferred by the SSPG." (PMID 35492025, 2022). "We also observed that this biomarker correlated with body composition and insulin resistance better than adiponectin or leptin alone." (PMID 36615734, 2022). "Bariatric surgery can improve insulin resistance and leptin secretion, thereby improving depression." (PMID 36387921, 2022). "LPS injection resulted in severe hypoglycaemia, insulin resistance, and increased levels of leptin and corticosterone." (PMID 35428321, 2022). "Leptin further links inflammation —by upregulating proinflammatory cytokines—and insulin resistance." (PMID 35057479, 2022). "Some of the mechanisms of increased arterial stiffness in subjects with higher BMI are insulin resistance, the accumulation of AGEs, and increased circulating leptin level." (PMID 34978636, 2022). "We found significant (p < 0.05) increases in serum levels of PCSK9, serum insulin, insulin resistance, and leptin at the end of Ramadan compared with pre-fasting levels." (PMID 35454343, 2022). "In our study, we analyzed many metabolic parameters to further evaluate the relationship between HOMA-IR and leptin levels, which is an important indicator of insulin resistance." (PMID 36143007, 2022). "In children at stages 2–4 of CKD, leptin was found to correlate positively with BMI and triglyceride levels, and negatively with HDLc and insulin resistance." (PMID 36289903, 2022). "In this study, serum resistin, TNF-α, and leptin levels were dramatically reduced by SRPE-3-Cr(III) treatment, indicating SRPE-3-Cr(III) alleviated insulin resistance by inhibiting the secretion of serum resistin, leptin, and TNF-α from adipocytes." (PMID 37073221, 2022).
Insulin resistance (continued). "In lipotoxic insulin resistance a plasma leptin threshold for replacement around 4 μg/l was initially suggested, but later analysis did not confirm a robust threshold." (PMID 35618782, 2022). "The effects of leptin and adiponectin were indirect and showed an inverse correlation with insulin resistance, triglycerides, and LDL-C." (PMID 35455483, 2022). "Leptin’s role in enhancing insulin sensitivity and improving insulin resistance in lipodystrophy and diabetic models has also been reported." (PMID 34996484, 2022). "Leptin has a potent effect on insulin signalling and treatment of ob/ob and other lipodystrophic mice with physiological leptin doses rescues insulin resistance." (PMID 35844058, 2022). "Previous research suggested that elevated leptin levels play an important role in insulin resistance." (PMID 36143007, 2022). "This fasting also impacts glucometabolic markers (e.g., adiponectin, leptin, insulin resistance, and serum insulin levels)." (PMID 35454343, 2022). "This study showed that increased leptin levels are associated with high HOMA-IR, which is an important index of insulin resistance among middle-aged and elderly populations in Taiwan." (PMID 36143007, 2022). "Consistent with an association between serum EMC10 and insulin resistance, serum EMC10 levels correlated positively with fasting plasma glucose, HbA1c, free fatty acids (FFA) and leptin, and inversely with serum adiponectin." (PMID 36443308, 2022). "Leptin levels are significantly low and correlate with insulin resistance markers in individuals with lipodystrophy, a condition defined by a lack of adipose tissue." (PMID 35386146, 2022). "Putting this information together, if a fasting person has high dietary intakes of carbohydrates and fat, this results in high glucose and insulin levels (i.e., insulin resistance), increases leptin, decreases adiponectin, and increases circulating PCSK9." (PMID 35454343, 2022). "Leptin is an adipokine expressed in adipose tissue, that is, involved in energy expenditure and the modulation of insulin resistance." (PMID 36034841, 2022). "These favorable effects on glycolipids, leptin sensitivity, and insulin resistance suggest an alternative treatment for complex diseases such as metabolic syndrome and cardiovascular disease." (PMID 36559300, 2022). "In conclusion, plasma leptin, insulin resistance and CRP levels in schizophrenic patients are closely related to metabolic disorders in schizophrenia patients." (PMID 36090349, 2022). "This study explored the correlation between plasma higher leptin levels, homeostasis model assessment of insulin resistance (HOMA-IR) index, hs-CRP and glycolipid metabolism in patients with chronic schizophrenia (CS)." (PMID 36090349, 2022). "Increasing evidence shows that hot flashes impact physical health and are associated with impaired lipid profiles, endothelial dysfunction, imbalanced adipocyte-derived hormones (leptin and adiponectin), and insulin resistance during menopause." (PMID 36260646, 2022). "So far, numerous scientific studies have shown that the placenta-derived hormones such as leptin, progesterone, cortisol, estrogen, placental growth hormone, and lactogen are involved in the initiation and progression of insulin resistance." (PMID 35743054, 2022). "Various factors such as autoimmunity, fertility, hormones like estrogen, gender, insulin resistance, and high BMI affect the relationship between thyroid function and leptin." (PMID 35510203, 2022). "The literature suggests that excess body weight accompanied by abnormal metabolic health parameters (e.g., body fat percent, waist-to-hip ratio, insulin resistance, and leptin) is related to a reduction in olfactory bulb volume." (PMID 35956353, 2022). "This study highlights elevated serum leptin levels in PCOS, and associations between serum leptin and PCOS-related hyperandrogenemia and insulin resistance." (PMID 35355566, 2022).
Insulin resistance (continued). "High leptin level and leptin resistance can increase insulin level, promote insulin resistance, affect the insulin signal transduction pathway of hepatocytes, and increase fatty acid content in hepatocytes, resulting in fatty liver occurrence." (PMID 35069014, 2022). "The release of excess saturated free fatty acids and pro-inflammatory cytokines from AT induces insulin resistance in peripheral and central systems as well as leptin resistance in the hypothalamus." (PMID 34959926, 2021). "Bodyweight, retroperitoneal fat mass, insulin resistance, leptin and triglyceride concentrations and adipocyte hypertrophy were higher in CD- compared to STD-fed rats." (PMID 33570456, 2021). "The observed eWAT changes were accompanied by reduced plasma leptin and increased plasma adiponectin levels over time, and improved insulin resistance (HOMA-IR)." (PMID 34444996, 2021). "PTSD is associated with low-density lipoprotein-cholesterol, cortisol, interleukin (IL)-2, IL-6, IL-8, leptin, insulin resistance, and tumor necrosis factor (TNF)-α9–12." (PMID 33674663, 2021). "Higher baseline cervical and chin-SAT correlated with increased WC, diastolic and systolic blood pressure, leptin, insulin, HbA1C, and homeostasis-model-assessment-of-insulin-resistance (HOMA-IR; p < 0.05 for all)." (PMID 34836081, 2021). "A human study in 2003 revealed that leptin levels were potentially related to insulin resistance and beta-cell function in diabetic patients." (PMID 35432804, 2021). "In healthy and obese children, the relationships between GAL serum levels and metabolic parameters (insulin, glucose, lipids, homeostasis model assessment-insulin resistance, leptin) have been studied." (PMID 33802616, 2021). "IL-17 also links inflammation with insulin resistance and adipocytes dysfunction; for instance, there is a reciprocal regulation between the pro-inflammatory adipokine leptin and IL-17." (PMID 34631754, 2021). "Level weight gain, visceral fat accumulation, blood lipid, TNF-α, leptin, IL-6 level reduction.Improved insulin resistance (with HOMA-IR)." (PMID 34641407, 2021). "On the other hand, the inability and dysfunctional adipose tissue cause decreased secretion of insulin-sensitizing adipokines, such as leptin and adiponectin, contributing to insulin resistance." (PMID 34407873, 2021). "Galantamine significantly inhibited TNF and leptin—two key mediators of the chronic inflammatory state and contributors to insulin resistance." (PMID 33776997, 2021). "In this study, we showed that experimental diets did not affect serum leptin levels, whereas stimulation with LPS significantly lowered serum leptin levels, demonstrating a close relationship between leptin and LPS-induced insulin resistance." (PMID 34682732, 2021). "Decreases in fasting blood glucose level, TG in the liver, TC, LDL, leptin, insulin, and insulin resistance were also noted." (PMID 33435282, 2021). "Although an association between leptin and T2DM was reported in Caucasian populations, its effect was less obvious when insulin resistance and other confounding variables were included into the analysis." (PMID 34368053, 2021). "As expected, heavier WD cotwins had higher LDL, hs-CRP, insulin resistance, and leptin levels and lower HDL and adiponectin levels than leaner WD cotwins, as has been reported before for weight-discordant MZ pairs." (PMID 34565451, 2021). "This process is obvious and rapid, once exposed to HFD, overexpression of SOCS3 can be detected in AgRP neurons, inducing energy imbalance, leptin, and insulin resistance, and hyper-appetite." (PMID 33763034, 2021). "Elevated leptin has been shown to induce leptin resistance, leading to the development of metabolic disorders, such as insulin resistance and dyslipidemia, as well as CVD." (PMID 33573042, 2021). "In particular, adiponectin and leptin are capable of decrease liver fat accumulation and insulin resistance." (PMID 36994336, 2021).
Insulin resistance (continued). "Insulin resistance is related to the adipocyte hormones (leptin and adiponectin) that mediate insulin-sensitizing effects through the activation of adenosine monophosphate dependent kinase (AMPK), PPARγ, and some other signaling pathways." (PMID 34805244, 2021). "Many mechanistic studies in this field focus on inflammatory cytokines, leptin signaling, insulin resistance and adipokine signaling." (PMID 33815828, 2021). "There is evidence that obese patients demonstrate low levels of plasma omentin-1, and its levels are negatively related to BMI, waist circumference, leptin levels, and insulin resistance." (PMID 34567888, 2021). "The observed phenomenon shed a promising light for the application of both inhibitors as protective agent against insulin resistance development, since the advantage of adiponectin over leptin has been shown to protect against metabolic disorders development." (PMID 34732209, 2021). "In another study, overactivation of the STAT/SOCS3 intracellular pathway by increased concentrations of leptin, resulting from growing adipose tissue, not only leads to leptin but also to insulin resistance at the level of CNS." (PMID 33562540, 2021). "Meanwhile, the increase in visceral fat will change the secretion mode of adipocytokines (including leptin, adiponectin, etc.), which plays a vital role in insulin resistance, dyslipidemia, prethrombotic state, and chronic inflammatory state." (PMID 34660733, 2021). "Lipoatrophic diabetes, caused by abnormal lipid homeostasis, results in less lipid storage in the adipose tissues and voracious appetite, with lower leptin secretion, higher blood triglyceride levels, and insulin resistance." (PMID 34310946, 2021). "High blood levels of leptin play a major role in insulin resistance by inducing the production of IL-6 and TNF-α." (PMID 34069933, 2021). "The increased adipose tissue will lead to metabolic changes, including leptin, resistin, and pro-inflammatory factors, leading to insulin resistance and other cardiovascular and cerebrovascular diseases." (PMID 34867792, 2021). "Oxidative stress induced by nocturnal intermittent hypoxia is reversible with CPAP therapy, leading to a significant reduction in leptin level (known as satiety hormone) and insulin resistance, respectively." (PMID 33499194, 2021). "It has been discovered earlier that the primary mediator of insulin resistance is abdominal adiposity which can deregulate the anti-diabetic hormone leptin." (PMID 34959910, 2021). "Several adipokines such as TNFα, adiponectin, leptin, and PEDF have been implicated as potential mediators of insulin resistance, both local and systemic." (PMID 34045558, 2021). "With the accumulation of fat, the adiponectin level is decreased, the leptin level is increased, and the insulin action is impaired, resulting in insulin resistance." (PMID 34679767, 2021). "Leptin also reversed lipodystrophy-induced insulin resistance and diabetic complications by regulating insulin signaling in mice." (PMID 34631690, 2021). "The fact that when adjusting by leptin this favorable association of the polymorphism with insulin and HOMA emerges supports the role of PPARγ in relationship with insulin resistance already at this age." (PMID 34887761, 2021). "Diabetic obese mice treated with TAN at doses of 200 mg/kg experience reductions in body weight, insulin resistance and lowered secretion of key inflammation markers, adiponectin, leptin, resistin, IL‐6, and MCP‐1." (PMID 33841818, 2021). "According to this, leptin has been shown to improve insulin resistance and hepatic steatosis in lypodystrophic mice." (PMID 34209386, 2021). "Leptin and resistin are the proinflammatory cytokines that promote insulin resistance via diverse mechanisms." (PMID 33917607, 2021). "For example, in addition to being an anticontractile adipokine, leptin also induces insulin resistance in brown adipocytes in culture." (PMID 34327871, 2021).